IGLV2-23 (immunoglobulin lambda variable 2-23)
Description:
V region of the variable domain of immunoglobulin light chains that participates in the antigen recognition. Immunoglobulins, also known as antibodies, are membrane-bound or secreted glycoproteins produced by B lymphocytes. In the recognition phase of humoral immunity, the membrane-bound immunoglobulins serve as receptors which, upon binding of a specific antigen, trigger the clonal expansion and differentiation of B lymphocytes into immunoglobulins-secreting plasma cells. Secreted immunoglobulins mediate the effector phase of humoral immunity, which results in the elimination of bound antigens. The antigen binding site is formed by the variable domain of one heavy chain, together with that of its associated light chain. Thus, each immunoglobulin has two antigen binding sites with remarkable affinity for a particular antigen. The variable domains are assembled by a process called V-(D)-J rearrangement and can then be subjected to somatic hypermutations which, after exposure to antigen and selection, allow affinity maturation for a particular antigen.
Synonyms: IGLV223; V1-7
Tractability: Antibody: its Gene Ontology location is reachable by antibodies, with high confidence; UniProt places it where antibodies can reach, with medium confidence; UniProt predicts a signal peptide or a membrane-spanning region.
Gene: Immunoglobulin variable (V) gene on chromosome 22 (22,697,789 to 22,698,407, forward strand). Ensembl gene ENSG00000211660.
Subcellular location: Secreted; Cell membrane
Pathways (Reactome):
Immune System: Antigen activates B Cell Receptor (BCR) leading to generation of second messengers; CD22 mediated BCR regulation; Classical antibody-mediated complement activation; FCERI mediated Ca+2 mobilization; FCERI mediated MAPK activation; FCERI mediated NF-kB activation; FCGR activation; Fc epsilon receptor (FCERI) signaling; Immunoregulatory interactions between a Lymphoid and a non-Lymphoid cell; Initial triggering of complement; Regulation of Complement cascade; Regulation of actin dynamics for phagocytic cup formation; Role of LAT2/NTAL/LAB on calcium mobilization; Role of phospholipids in phagocytosis
Disease: FCGR3A-mediated IL10 synthesis; FCGR3A-mediated phagocytosis; Potential therapeutics for SARS
Hemostasis: Cell surface interactions at the vascular wall
Vesicle-mediated transport: Scavenging of heme from plasma
Gene Ontology:
Molecular function: antigen binding
Biological process: immune response
Cellular component: extracellular region; immunoglobulin complex; plasma membrane
Homologues: Paralogues in human: IGLV2-14 (94% identical), IGLV2-11 (91% identical), IGLV2-8 (90% identical), IGLV2-18 (88% identical), IGLV1-40 (73% identical), IGLV2-33 (70% identical), IGLV1-50 (69% identical), IGLV1-44 (67% identical), IGLV1-47 (66% identical), IGLV1-36 (65% identical), IGLV6-57 (65% identical), IGLV1-51 (64% identical), and 81 more.
Diseases named in the same sentence as IGLV2-23 in open-access papers:
IGLV2-23 is named in the same sentence as 2 diseases in open-access papers, as found by Europe PMC text mining. Sharing a sentence is not in itself a finding about the gene and the disease.
IGLV2-23 shares sentences with these, for which no sentence is quoted: breast carcinoma (1 paper); prostate carcinoma (1).